MCM2 (minichromosome maintenance complex component 2)
Diseases named in the same sentence as MCM2 in open-access papers (continued):
Sharing a sentence is not in itself a finding about the gene and the disease.
lung carcinoma (19 papers, 2009 to 2024). "In this study, we aimed to identify the diagnostic, therapeutic, and prognostic value of the MCM2–10 genes in patients with lung cancer." (PMID 35360518, 2022). "MCM2, 3 and 6 that were overexpressed in our material are associated to poor prognosis in lung cancer, astrocytoma and craniopharyngeal carcinoma respectively." (PMID 19662092, 2009). "A recent study showed that MCM2 was implicated in lung cancer as an oncogene." (PMID 33505310, 2020). "In total, 1144 samples from TCGA were analyzed, and the percentage of genetic alterations in MCM2–10 for lung cancer varied from 1.1% to 5%." (PMID 35360518, 2022). "In future studies, large clinical datasets are required to verify our findings, and the role of MCM2–10 in the pathogenesis of lung cancer should be further explored." (PMID 35360518, 2022). "Accordingly, in this study, bioinformatic methods were used to analyze online public databases to assess the expression of MCM2–10 genes in patients with lung cancer and the relationship between this expression and tumor prognosis." (PMID 35360518, 2022). "The correlation between the MCM2–10 expression and lung cancer prognosis was evaluated using Cox regression analysis." (PMID 35360518, 2022). "The cBioPortal online tool was then used to evaluate the frequency of MCM2–10 alteration in lung cancer." (PMID 35360518, 2022). "A t-test of paired samples showed that the expression of MCM2, 3, 4, 5, 6, 7, 8, and 10 in lung cancer was higher than the average level of normal, and the difference was statistically significant (p < 0.001)." (PMID 35360518, 2022). "The deregulation of MCM2 impacts lung cancer cell proliferation, the cell cycle, and cell migration." (PMID 35464867, 2022). "The expression of MCM2, 3, 4, 5, 6, 7, 8, and 10 in lung cancer was higher than that for normal samples." (PMID 35360518, 2022). "Our findings demonstrated that MCM2-8 and 10 were highly expressed in lung cancer, and only MCM5 affected the prognosis of patients with lung cancer." (PMID 35360518, 2022). "The prognostic value of MCM2 was confirmed in pancreatic cancer, lung cancer, multiple myeloma, and oral cancer." (PMID 34195183, 2021). "Analysis of the p-MCM2/MCM2 ratio between early and advanced tumor stages of CRC and lung cancer groups resulted in a 1.27-fold increase (P < 0.01), and 1.44-fold elevation (P < 0.001) of p-MCM2/MCM2 ratio, respectively." (PMID 32469983, 2020). "The regulatory role of MCM2 in lung cancer has been extensively investigated in a integrate analysis of phospho-proteome and proteome of overexpressed and silenced MCM2 lung cancer cells." (PMID 31784636, 2019). "In order to obtain a more comprehensive understanding of the regulatory networks of MCM2-modulated protein phosphorylation in lung cancer cells, the global proteome was investigated using iTRAQ labeling on 48-h silenced-MCM2 H1299 cells." (PMID 29038488, 2017). "To ascertain the stimulatory effect of MCM2 on lung cancer cells, we used small interfering RNA (siRNA) to knock down MCM2 in H1299 cells, which caused a noticeable decline in cell proliferation." (PMID 29038488, 2017). "Integrating our analyses of the phosphoproteome and global proteome for two lung cancer cell lines in response to MCM2 provides a more comprehensive description of MCM2 downstream events and has allowed us to detect potential targets for drug development." (PMID 29038488, 2017). "Our study has established a global functional distribution of the identified phosphoproteins and the phosphorylation sites involved in both the overexpression and the silencing of MCM2 in lung cancer cells." (PMID 29038488, 2017). "The RNA-seq datasets from The Cancer Genome Atlas (TCGA) revealed that MCM2 overexpression is correlated with poor survival rate in lung cancer patients." (PMID 29038488, 2017). "Understanding the molecular interactions of MCM2 in lung cancer cells enhances our capacity to therapeutically target cancer-specific phosphoproteins." (PMID 29038488, 2017).
lung carcinoma (continued). "Despite efforts to comprehend how phosphorylation regulates initiation of DNA synthesis, the biological networks of MCM2-7 in lung cancer cells via protein phosphorylation remain unmapped." (PMID 29038488, 2017). "The protein phosphorylation response to MCM2 in lung cancer remains uncharacterized; however, MCM2 has been proposed as an excellent proliferation marker in many types of cancer." (PMID 29038488, 2017). "Colony formation was monitored to investigate the long-term effect of MCM2 on lung cancer cell proliferation, and the results indicated that overexpression of MCM2 improved colony-forming ability." (PMID 29038488, 2017). "We found that the deregulation of MCM2 is involved in lung cancer cell proliferation, the cell cycle, and migration." (PMID 29038488, 2017). "Previous studies have demonstrated that MCM2 knockdown leads to cell cycle arrest in colon and lung cancer cells." (PMID 29038488, 2017). "In summary, our quantitative study of the phosphoproteome and proteome provides a comprehensive examination and validation of the effects of MCM2 protein expression in two lung cancer cell lines with opposing perturbations." (PMID 29038488, 2017). "Moreover, MCM2 is thought to be involved in cancer metastasis by regulating cell migration and invasion, not limited to lung cancer but also identified in glioma." (PMID 38454443, 2024). "Moreover, inhibition of MCM3 or MCM2, one of the other MCMs members, suppresses transition of G1 to S phase in colorectal cancer or lung cancer cells." (PMID 37817427, 2023). "MCM2 plays a role in the proliferation, circulation, and migration of lung cancer cells." (PMID 35360518, 2022). "However, a correlation between the MCM2–10 gene expression and immune infiltration in lung cancer has rarely been reported." (PMID 35360518, 2022). "In vitro studies indicate that MCM2 silencing inhibits cell proliferation by affecting the G1/S transition and conversely the overexpression of MCM2 promotes cell proliferation in lung cancer cells; moreover, MCM2 knockdown inhibits cell migration in lung cancer cells." (PMID 33499054, 2021). "In lung cancer, high expression levels of MCM2, MCM5, MCM6, and MCM7 could be useful prognostic markers." (PMID 31514295, 2019). "Furthermore, HMGA1S99 phosphorylation was found to be differentially expressed under MCM2 perturbation in opposite directions, and plays an important role in regulating lung cancer cell proliferation." (PMID 29038488, 2017). "Our observations that MCM2 knockdown deregulated the G1/S transition in lung cancer cells confirmed our hypothesis that MCM2 regulates the initiation of DNA replication, leading to cell proliferation." (PMID 29038488, 2017). "Our results provide a comprehensive insight into the regulatory role of MCM2 in lung cancer, and also reveal that MCM2 promotes cell proliferation might possibly via the regulation of high mobility group protein HMG-I/HMG-Y (HMGA1) phosphorylation." (PMID 29038488, 2017). "However, the biological networks of MCM2 in lung cancer cells via protein phosphorylation remain unmapped." (PMID 29038488, 2017). "Additional study of MCM2 networks in lung cancer cells might expand our knowledge regarding lung cancer drug development and provide additional targets." (PMID 29038488, 2017). "To uncover MCM2-regulated functional networks in lung cancer, we performed multi-dimensional proteomic approach by integrating analysis of the phosphoproteome and proteome, and identified a total of 2361 phosphorylation sites on 753 phosphoproteins, and 4672 proteins." (PMID 29038488, 2017). "In this study, we perform large-scale analysis of the phosphoproteome and proteome to characterize and interpret MCM2, in an attempt to establish a global functional distribution of the identified phosphoproteins and phosphosites in both overexpressed and silenced MCM2 lung cancer cells." (PMID 29038488, 2017).
lung carcinoma (continued). "Further evidence of the role of MCM2 in regulating cell migration was obtained by using a Transwell assay to evaluate migration ability in MCM2-overexpressing A549 cells and MCM2-silenced H1299 cells, which showed that MCM2 knockdown inhibits cell migration in lung cancer cells." (PMID 29038488, 2017). "Correlation analysis between the MCM2-10 expression and OS revealed that only MCM5 was closely related to poor OS in patients with lung cancer." (PMID 35360518, 2022). "RNAi-mediated depletion of MCM2 induced G2/M-phase arrest in GBM and HCC cells, and G1-phase arrest in colon cancer and lung cancer cells." (PMID 36303105, 2022). "The Kaplan–Meier survival analysis was performed to plot the OS of colon and lung cancer patients with abnormal levels of CALU, AURKA, and MCM2, in separate form and as a panel." (PMID 32469983, 2020). "In order to comprehensively analyze the role of MCM2 in lung cancer, two NSCLC cell lines, A549 and H1299 with different endogenous expression levels of MCM2 were used." (PMID 29038488, 2017). "Transcriptomic alterations that occur during lung cancer development include over-expressed cell cycle related genes like E2F3, BUB3, CDK4, MCM2, MCM3, and MCM7 as summarized by Powell and Borczuk." (PMID 26930711, 2016). "There are several treatments targeting MCM2 in colon and lung cancer, such as Trichostatin A and Lovastatin57,58; however, the molecular regulation in response to MCM2 via protein phosphorylation in lung cancer has not been fully elucidated." (PMID 29038488, 2017). "Although MCM2 and MCM5 both play as the DNA entry gate of the MCM complex to regulate the initiation of DNA replication and might be important in regulating lung cancer, we only focused on studying MCM2." (PMID 29038488, 2017).
hepatocellular carcinoma (18 papers, 2009 to 2025). A malignant tumor that arises from hepatocytes. "A study of hepatocellular carcinoma (HCC) showed that long noncoding RNA FTX (lnc-FTX) binds to MCM2 and results in the arrest of DNA replication, causing lower proliferation of HCC cells." (PMID 40005158, 2025). "Based on the previous findings by our team and other researchers, this study attempted to further explore the role of MCM2 for the stemness and self-renewal ability of hepatocellular carcinoma cells and the regulatory mechanisms involved." (PMID 36243809, 2022). "The expression levels of MCM2 in several hepatoma cell lines and normal hepatocyte lines were examined using qPCR." (PMID 36243809, 2022). "Results from RT-PCR showed that MCM2 mRNA expression levels were higher in the indicated hepatoma cell lines than that in normal liver HL7702 cells." (PMID 35093119, 2022). "The results of these assays suggested that the addition of Super-TDU reversed the effect of MCM2 on stemness and the self-renewal ability of the hepatocellular carcinoma cells." (PMID 36243809, 2022). "MCM6, another subunit of the MCM2-7 complex, was recently found to be up-regulated in hepatocellular carcinoma (HCC)." (PMID 33505310, 2020). "FTX was reported to inhibit hepatocellular carcinoma proliferation and metastasis by binding MCM2 and miR-374a." (PMID 30764831, 2019). "In our study, we found that in hepatocellular carcinoma tissues, MCM2 expression was highly correlated with YAP expression, and that MCM2 interference inhibited the Hippo signaling pathway by blocking YAP entry into the nucleus, thereby increasing cellular resistance to sorafenib." (PMID 36243809, 2022). "YTHDF2 stabilizes the transcription of maintenance protein 2 (MCM2) and maintenance protein 5 (MCM5) in microchromosomes, promoting hepatocellular carcinoma progression in hepatitis B virus-infected individuals." (PMID 38711079, 2024). "Unlike promoter/enhancer demethylation-mediated upregulation of ITPR3, MCM2 and NUP37 in hepatocellular carcinoma." (PMID 36694230, 2023). "Previous studies showed that MCM2 and MCM7 promote hepatocellular carcinoma cell stemness and tumor progression via hippo signaling and cyclin D1-dependent signaling, respectively, and overexpression of them correlates with poor prognosis in HCC." (PMID 38343446, 2023). "We also assessed the expression profiles of MCM2 and NUP37 in 5 different hepatoma cell lines and one normal liver cell line (HL7702)." (PMID 35093119, 2022). "In our present work, firstly, we comprehensively revealed and validated the expression profile of MCM2 in both clinical HCC samples and human hepatoma cell lines." (PMID 35093119, 2022). "Minichromosome maintenance complex component 2 (MCM2) and nucleoporin 37 (NUP37) were overexpressed in human HCC tissues and hepatoma cell lines." (PMID 35093119, 2022). "A significant rise in Ki67 expression has also been observed in regenerative nodular lesions of cirrhotic liver that progressed to hepatocellular carcinoma, but not for Mcm2 and geminin." (PMID 19293805, 2009). "In an HBV-related hepatocellular carcinoma (HCC) model, YTHDF2 stabilizes MCM2 and MCM5 transcripts in an m6A-dependent manner." (PMID 40271153, 2025).
colon cancer (17 papers, 2013 to 2025). "In terms of colon cancer, MCM2 is a highly conserved minichromosome maintenance proteins that plays a role as a diagnostic marker and therapeutic target for colon cancer." (PMID 39758846, 2024). "In colon cancer, MCM2 expression is regulated by miR‐195‐5p and miR‐497‐5p, which are downregulated in cancer tissues and cultured cancer stem cells." (PMID 37517032, 2023). "The inhibitory effect of TSA on MCM2 was further confirmed by an RT-PCR array in the colon cancer cell, HCT116." (PMID 36303105, 2022). "For example, nuclear factor κB (NF-κB), a transcription factor that has been demonstrated in multiple solid and hematological cancers, has been reported to regulate MCM2 to maintain the stem cell-like properties of colon cancer cells." (PMID 35693940, 2022). "It has been found that the MCM-2 target gene of trichostatin-a is a novel therapeutic target in colon cancer cells." (PMID 29020948, 2017). "Trichostatin A, a classical histone deacetylase inhibitor, could downregulate the expression of MCM2, and the silencing of MCM2 in colon cancer cells could induce cell cycle arrest and apoptosis as reported in a previous study." (PMID 34484287, 2021). "Furthermore, MCM2-7 complex members were abnormally up-regulated in various cancers, such as gastric cancer and colon cancer." (PMID 27695057, 2016). "In colon cancer, CACYBP enhances proliferation by interacting with Skp1 to degrade p27ˆKip1, while in cholangiocarcinoma, it promotes progression by inhibiting MCM2 ubiquitination and activating the Wnt/β-catenin signaling pathway." (PMID 40167359, 2025). "In particular, UBC, MCM2, and COPS5 show stronger dependencies in colon cancer comparing with the mean across all cell lines (six sigma or greater dependency)." (PMID 30723737, 2019). "RT-PCR showed that MCM2 gene expression is downregulated upon TSA treatment and that knockdown of Mcm2 induces cellular apoptosis in colon cancer cells." (PMID 25243149, 2014). "In addition, depletion of MCM2 inhibited migration and invasion in MB and GBM and induced apoptosis in colon cancer and HCC." (PMID 36303105, 2022). "In previous study, MCM2, MCM3 and MCM4 were dysregulated in malignant salivary gland tumours, gastric cardiac cancer, thyroid malignancy, non-small cell lung cancer, malignant melanoma, colon cancer, promyelocytic leukemia, cervical squamous cell carcinoma." (PMID 24386425, 2013).
glioma (17 papers, 2013 to 2025). A benign or malignant brain and spinal cord tumor that arises from glial cells (astrocytes, oligodendrocytes, ependymal cells). "High MCM2 expression was found to be strongly associated with poor overall survival in patients with high-grade glioma in our current study, as well as previous studies." (PMID 32047515, 2019). "Our study indicates for the first time that high MCM2 mRNA expression appears to be strongly associated with poor overall survival in high grade glioma." (PMID 25046975, 2014). "High MCM2 mRNA expression appeared to be strongly associated with poor overall survival in patients with high grade glioma." (PMID 25046975, 2014). "Additionally, MCM2 is associated with many types of cancer, including acute lymphocytic leukemia, gallbladder cancer, and glioma." (PMID 34484287, 2021). "Corresponding with a previous report, Notch inhibition via short-hairpin RNA (shRNA) targeting Notch2 downregulates MCM2 and p21 expression, hence inducing cell cycle arrest in U87 human glioma cells." (PMID 36012128, 2022). "Distribution of glioma cells expressing MCM2 and CDC45 which confer the helicase activity on GINS complex by forming a CMG complex was also examined." (PMID 30465075, 2019). "In the present study, it was found that Notch2 signaling in U87 human glioma cells increased the proportion of cells in the S phase and upregulated MCM2 and cyclin D1 protein expression levels; however, p21 protein expression was downregulated." (PMID 25323114, 2014). "MCM2 and MCM5 are two members of the Minichromosome Maintenance (MCM) family; the entire family of MCMs is promising in glioma prognosis and diagnosis." (PMID 40507925, 2025). "Univariate and multivariate analyses uncovered that MCM2, MCM4, MCM6, MCM7 expression, tumor grade, and age were independent factors that influence the clinical outcome of glioma patients." (PMID 36465369, 2022). "Most notably, MCM2, MCM3 and MCM7 aberrations in glioma tumors portend a particularly aggressive clinical behavior." (PMID 25046975, 2014). "An immunoreactive band of MCM2, MCM3 and MCM7 were seen in all six cases of gliomas, MCM2, MCM3 and MCM7 expressions were significantly higher in malignant tissues than in tissues with low malignant potential." (PMID 25046975, 2014). "To confirm the specificity of the qPCR results, we characterized MCM2, MCM3, MCM7, as well as β-actin as a loading control, in six glioma samples for which freshly frozen materials were available." (PMID 25046975, 2014). "In conclusion, the results suggest that MCM2, MCM3 and MCM7 play important roles in glioma tumor progression." (PMID 25046975, 2014). "Univariate and multivariate analyses revealed that MCM2, MCM4, MCM6, MCM7 expression and tumor grade, 1p/19q codeletion, primary therapy outcome, and age were independent factors that influenced the clinical outcome for glioma patients." (PMID 36465369, 2022). "Univariate and multivariate analyses revealed that MCM2, MCM4, MCM6, MCM7 expression and tumor grade, 1p/19q codeletion, primary therapy outcome, and age were independent factors correlated with poor clinical outcomes of glioma patients." (PMID 36465369, 2022). "Frequency of MCM2- or CDC45-positive glioma cells was independent of their spatial relation to the ischemic necroses." (PMID 30465075, 2019). "Thus the expression level of MCM2, MCM3 and MCM7 reveal information on the survival probability for patients with glioma beyond that revealed by grade alone." (PMID 25046975, 2014). "MCM2, MCM3 and MCM7 proteins expression is also known to be an important tool for estimating tumor proliferation and a useful adjunct to the routinely used proliferation markers for glioma diagnosis." (PMID 25046975, 2014). "In contrast, MCM2 and CDC45 were almost ubiquitously expressed, both inside and outside the peri-necrotic areas, in proliferating as well as non-proliferating glioma cells." (PMID 30465075, 2019).